ZNF414 (zinc finger protein 414)
Description:
May be involved in transcriptional regulation.
Synonyms: MGC15716; Zfp414
Tractability: PROTAC: its protein half-life has been measured.
Gene: Protein-coding gene on chromosome 19 (8,509,678 to 8,514,167, reverse strand). Ensembl gene ENSG00000133250.
Subcellular location: Nucleus
Subcellular location (Human Protein Atlas): Nucleoplasm
Gene Ontology:
Molecular function: protein binding; DNA-binding transcription factor activity
Biological process: regulation of DNA-templated transcription
Cellular component: nucleus
Genetic constraint (gnomAD): Loss-of-function variants: 33 observed, 24.21 expected, observed/expected ratio (o/e) 1.36, 90% interval 1.03 to 1.79. The synonymous counts are far from expectation, so gnomAD's model fits this gene poorly and the ratio says little. Missense variants: 589 observed, 387.08 expected, observed/expected ratio (o/e) 1.52, 90% interval 1.42 to 1.63. Synonymous variants: 256 observed, 171.64 expected, observed/expected ratio (o/e) 1.49, 90% interval 1.35 to 1.65.
Homologues: Orthologues: chimpanzee ZNF414 (99% identical), macaque ZNF414 (95% identical), dog ZNF414 (89% identical), pig ZNF414 (89% identical), rabbit ZNF414 (74% identical), mouse Zfp414 (62% identical), rat Zfp414 (50% identical), tropical clawed frog znf414 (32% identical), zebrafish znf414 (23% identical).